IGF1R (insulin like growth factor 1 receptor)
Diseases named in the same sentence as IGF1R in open-access papers (continued):
Sharing a sentence is not in itself a finding about the gene and the disease.
Insulin resistance (continued). "The animals exhibited higher insulin levels, insulin resistance (indicated by increased HOMA-IR), lower IGF-1 levels, and increased IGF-1R phosphorylation." (PMID 37569816, 2023). "To explore the effect of RES on ovarian insulin resistance, we detected the expressions of IGF1 and IGF1R." (PMID 36742000, 2022). "Curiously, insulin resistance has been related to serum levels of the growth factor IGF1 and its receptor IGF1R – components of the growth hormone (GH) and energy metabolisms." (PMID 36506063, 2022). "Due to the existence of insulin resistance in T2DM, IGF-1 and insulin are at a high level over a long period of time, with secondary elevation in IGF-1R." (PMID 35035440, 2022). "The insulin resistance results in increased production of IGF-1, resulting in upregulation of the IGF-1R/AKT pathway, promoting carcinogenesis, angiogenesis, migration, and invasion." (PMID 35008602, 2021). "Recently, seven markers based on the BMI-sensitive pathway of insulin resistance, adipoR1, adipoR2, ObR, IRβ, IRS-1, IGF-1R, and IGF-2R, have been proposed to develop a new molecular typing system for endometrial cancer." (PMID 31440472, 2019). "Relatively elevated concentrations of insulin induced by insulin resistance boosts hepatic IGF-I synthesis and increases circulating IGF-I activity, which then also binds to IR, IGF-1R, and IR/IGF-1R to enhance the signaling." (PMID 31847392, 2019). "In these studies, BCAA supplementation suppressed liver carcinogenesis by reducing insulin resistance, ameliorating hepatic steatosis, inhibiting activation of the IGF/IGF-1R axis, and attenuating hepatic inflammation." (PMID 25789501, 2015). "We implemented a combined bioinformatics analysis to retrieve a set of ceRNA networks (LncRNA-RP11-773H22.4, miR-1, miRNA-3163, which is related to insulin resistance and their targeting signaling pathway genes RET, IGF1R, GLUT4, AKT2 and mTOR mRNAs) from public databases." (PMID 34360895, 2021). "It includes the emergence of insulin resistance, other than variations in the insulin-like growth factor-1 (IGF-1)/IGF-1 receptor (IGF-1R) axis, occurrence of adipocytokine imbalance, the state of chronic tissue inflammation, and the induction of cellular oxidative stress." (PMID 32063842, 2019). "Several pathophysiological mechanisms, including the emergence of insulin resistance, activation of the IGF/IGF-1R axis, development of adipokine imbalance, chronic inflammation, and induction of oxidative stress, link metabolic syndrome and hepatocarcinogenesis." (PMID 25789501, 2015). "In our study, hsa-miR-26b-5p, hsa-let-7i-5p, hsa-miR-100-5p and hsa-miR-143-3p were found to be interacting with IGF1R and/or IGF1 gene, suggesting that these miRNAs might play a role in this insulin resistance metabolism, in addition to diabetic complications." (PMID 36506063, 2022). "Since estrogens are recognized key regulators of energy balance and glucose homeostasis, they could protect females but not males on HFD to develop insulin resistance, independently of the IGF1R signaling activity." (PMID 36353242, 2022). "Therefore, treatments targeting abnormal glucose metabolism, insulin resistance, and IGF-1/IGF-1R signaling axis may exert potential therapeutic effects to decrease the tumor burden and the metastasis risks of intraocular malignancies." (PMID 36003786, 2022). "Both TSHR and IGF1R could activate PI3K/AKT pathway, regulating insulin resistance." (PMID 34524974, 2021). "Although the affinity of IGF-1R for insulin is lower compared with IGF-1, high concentrations of insulin, which are often observed in patients and animal models with insulin resistance, may affect intracellular signaling pathways dependent on IGF-1R or hybrid receptors." (PMID 25352918, 2014).
Insulin resistance (continued). "In addition, IGF1R blockade might also determine the dysregulation of IGF1R/IGF1/GH, which might determine the inhibition of IGF1 hypoglycemic effect and/or a compensatory increase in circulating GH, leading to increased liver glucogenesis and insulin resistance." (PMID 34440844, 2021). "MKR mice, lacking insulin-like growth factor 1 receptor (IGF-1R) signaling in skeletal muscle, are lean yet hyperlipidemic, hyperinsulinemic, and hyperglycemic, with severe insulin resistance and elevated hepatic and skeletal muscle levels of triglycerides." (PMID 21379576, 2011).
non-small cell lung carcinoma (104 papers, 2006 to 2025). A group of at least three distinct histological types of lung cancer, including non-small cell squamous cell carcinoma, adenocarcinoma, and large cell carcinoma. "A meta-analysis has also shown that IGF-1R expression is an unfavorable factor for survival in non-small cell lung cancer (NSCLC) patients, and is associated with smoking status and tumor size." (PMID 38540176, 2024). "Alterations in IGFBP2 expression are associated with resistance to both anti-IGF1R agents and dasatinib in rhabdomyosarcoma and non-small cell lung cancer cells, respectively." (PMID 33673232, 2021). "Ceritinib (an off-target IGF-1R antagonist) was approved by the FDA in 2014 for the treatment of ALK-mutated non-small cell lung cancer, while teprotumumab (an IGF-1R antagonist) was approved in 2020 for the treatment of active thyroid eye disease (TED, also known as Graves’ ophthalmopathy)." (PMID 37240591, 2023). "Single nucleotide mutations in the ligand binding site of IGF1R have been associated with development of various cancers, including non-small-cell lung cancer and multiple myeloma and may merit exploration for a possible role in the development of fibrosing lung disease." (PMID 31765403, 2019). "This is reminiscent of a report from Ajona and colleagues, who demonstrated that the combined inhibition of IGF1R and PD-1 synergistically reduced tumor growth in mice injected with non-small-cell lung cancer (NSCLC) cells." (PMID 38892104, 2024). "IGF-1R is currently being evaluated as a pharmacological target in clinical trials, including non-small-cell lung cancer (NSCLC)." (PMID 39638246, 2024). "Previously, linsitinib has been assessed in vivo to examine the effect on glucose uptake in non-small cell lung carcinoma xenografts, showing that at 60 mg/kg, linsitinib inhibited growth in IGF1R and IR positive tumours." (PMID 36920947, 2023). "For instance, LINC00324 overexpression acts as a miR-139 sponge, thereby releasing Insulin-like Growth Factor-1 Receptor (IGF1R) from miR-139 regulation and increasing the IGF1R protein expression in non-small-cell lung cancer." (PMID 35269391, 2022). "Figitumumab, an IGF1R monoclonal antibody, was investigated in Phase 3 clinical trials in combination with carboplatin and paclitaxel for the treatment of advanced non-small-cell lung cancer (NSCLC)." (PMID 33911195, 2021). "miRNA-140 has an inhibitory effect on the growth and metastasis of non-small-cell lung cancer cells, and its target is insulin-like growth factor 1 receptor." (PMID 33628799, 2021). "Silencing of IGF1R in human non-small cell lung cancer A549 cells led to downregulation of 59 miRNAs and upregulation of 13 miRNAs, including miR-497-3p, indicating a regulatory reciprocity between IGF1R and miR-497-3p." (PMID 33575847, 2021). "The previous studies demonstrated that DPT induced apoptosis by inhibiting the IGF1R/PI3K/Akt signaling pathway in human non-small cell lung cancer and glioblastoma multiforme cells." (PMID 32961992, 2020). "In non-small cell lung cancer, IGF1R hyperactivity is related to acquired resistance to erlotinib, and simultaneous inhibition of EGFR and IGF1R is effective to prevent and also to overcome erlotinib resistance." (PMID 32796636, 2020). "Subsequent chemical lysis of EVs on-chip enabled analysis of intravesicular biomarkers by ELISA, showing that non-small-cell lung cancer patients had a significantly elevated level of IGF-1R than healthy individuals." (PMID 28436447, 2017). "The practical feasibility of combination ALK/IGF-1R inhibition as a clinical strategy has been given a boost by recent research into the IGF-1R inhibitor AXL1717 in advanced non-small cell lung cancer." (PMID 29066738, 2017). "They successfully demonstrated this method to assess the total expression and phosphorylation levels of insulin-like growth factor 1 receptor (IGF-1R) in non-small-cell lung cancer patients." (PMID 29258216, 2017).
non-small cell lung carcinoma (continued). "Epidermal growth factor receptor (EGFR) and insulin-like growth factor 1 receptor (IGF-1R) both overexpressed on non-small cell lung cancer (NSCLC) and are known cooperatively to promote tumor progression and drug resistance." (PMID 28460483, 2017). "IGF1 receptor (IGF1R) expression has been used as a reporter of the clinical significance of non-small-cell lung carcinoma (NSCLC)." (PMID 27213344, 2016). "miR-140-5p expression is also reduced in non-small cell lung cancer, and it suppresses tumor growth and metastasis by targeting IGF1R." (PMID 27588393, 2016). "Herein, we conducted a study to validate the effect of Figitumumab (CP), an anti-IGF-1R mAb, in a panel of non-small cell lung cancer (NSCLC) cell lines." (PMID 27488947, 2016). "Gene expression analyses suggested insulin like growth factor receptor (IGF-1R) signaling to be instrumental in controlling anti-tumor efficacy of these compounds in non-small cell lung cancer (NSCLC)." (PMID 27384680, 2016). "LL-2003 effectively suppressed IGF-1R and Src and induced apoptosis in various non-small cell lung cancer cells." (PMID 26515601, 2015). "MiR-140 has also been found to suppress both the metastasis as well as the growth of tumours in patients with non-small cell lung cancer by targeting the insulin-like growth factor 1 receptor." (PMID 26355751, 2015). "According to previous reports demonstrating the implication of insulin-like growth factor receptor (IGF-1R) signaling in non-small cell lung cancer (NSCLC), in this study, the potential prognostic values of IGF-1R expression/activation were analyzed." (PMID 25944691, 2015). "The compound, LL-2003, exhibited promising antitumor effects in vitro and in vivo; it effectively suppressed IGF-1R and Src and induced apoptosis in various non-small cell lung cancer cells." (PMID 26515601, 2015). "Lack of efficacy and several side effects such as hyperglycemia led to a premature discontinuation of the phase III IGF1R targeting therapy study in non-small cell lung cancer." (PMID 24809298, 2014). "Disappointing results have also been reported for other anti-IGF-1R antibodies in the treatment of non-small-cell lung cancer (NSCLC)." (PMID 23921573, 2013). "One of the most studied IGF-1R antibodies is CP-751871 (Pfizer) and it showed rather promising activity in a phase II study in patients with advanced non-small cell lung cancer." (PMID 21729319, 2011). "The efficacy of the treatment has not been fully explored thus far, but encouraging data have been registered in a phase-II study concerning the use of an anti-IGF1R antibody in non-small-cell lung cancer." (PMID 20924377, 2010). "The shortened transcripts were sufficient to increase its protein turnover without increasing its transcript level, suggesting that 3′ UTR shortening of IGF1R could be a mechanisms that promotes its protein expression in Non-small cell lung cancer(NSCLC)." (PMID 36816917, 2023). "LINC00324 have been reported to influence cell proliferation and invasion of several tumors and could regulate the IGF1R to affect non-small cell lung cancer cell invasion." (PMID 34408984, 2021). "LL28 effectively inhibits both IGF1R- and Src-dependent signaling pathways and has promising therapeutic potential in vitro against a panel of non-small cell lung cancer (NSCLC) cell lines and in vivo in tumor xenograft and mutant Kras-driven lung tumorigenesis models with marginal toxicity." (PMID 29455661, 2018). "Data regarding IGF1R prognostic value in non-small cell lung cancer (NSCLC) are inconsistent." (PMID 26884344, 2017). "miR-30a regulated PI3K/AKT pathway by directly target IGF1R in non-small cell lung cancer." (PMID 29212217, 2017). "Particularly, loss of IGFBP2 is associated with resistance to anti-IGF1R treatment due to hyperactivation of IGF signaling in rhabdomyosarcoma, while overexpression of IGFBP2 drives dasatinib resistance through activation of FAK in non-small cell lung cancer cells." (PMID 33673232, 2021).
non-small cell lung carcinoma (continued). "The heterodimerization of EGFR with IGF1R in response to treatment with the EGFR TK inhibitor erlotinib has been described in non-small cell lung carcinoma (NSCLC) cells and is related to the subsequent development of drug resistance." (PMID 24212818, 2011). "It was reported that activation of the IGF1R/STAT3 pathway resulted in the upregulation of ALDH1, which in turn enhanced the stemness and radioresistance of non-small cell lung cancer." (PMID 39394189, 2024). "A recent study reported that IL-6 can induce EMT of non-small cell lung cancer cells by STAT3 activation and insulin-like growth factor-1 receptor (IGR-1R)." (PMID 34064322, 2021). "In non-small cell lung cancer, IGF-1 treatment of erlotinib-inhibited cells increased IGF1R/EGFR heterodimerization, leading to mTOR-mediated synthesis of EGFR and survivin, which counteracted the antiproliferative effects of Erlotinib." (PMID 30729097, 2019). "Moreover, IGF-1/IGF-1R antibodies are well tolerated in clinical trials but fail to generate overall therapeutic advantages in patients with small cell lung cancer or in patients with non-small cell lung cancer by combination with chemotherapy or tyrosine kinase inhibitors (TKIs)." (PMID 30018981, 2018). "The kinetics of ligand-induced nuclear translocation of IGF-1R is similar between DU145 cells and non-small cell lung cancer cells (H1299)." (PMID 27275536, 2016). "Shin and colleagues in 2013 tested the effectiveness of the anti-IGF1R antibody cixutumumab (cix) on a panel of human head and neck squamous cell carcinoma (HNSCC) and non-small cell lung cancer (NSCLC) cell lines." (PMID 25699021, 2015). "We found that glucosamine inhibited the growth of human non-small cell lung cancer (NSCLC) cells and negatively regulated the expression of IGF-1R and phosphorylation of Akt." (PMID 24438088, 2014). "In several non-small cell lung cancer (NSCLC) cell lines, IGFBP-3 acts as a potent inhibitor of IGF-1R signaling by interfering with both the MAPK and PI-3K/Akt signaling pathways, resulting in growth arrest and inducing apoptosis." (PMID 23185474, 2012). "Down-regulation of p-Akt by anti-IGF-1R antibodies occurs in cells of many different lineages, including small cell lung cancer (SCLC), acute myeloid leukemia, and non-small cell lung cancer." (PMID 22022506, 2011). "Given that IGF-1 truncation by DPP-IV affects the activation of IGF-1R, we next investigated the expression levels of DPP-IV in human non-small-cell lung cancer tissues with quantitative RT–PCR." (PMID 23675206, 2010). "We used a panel of 22 non-small cell lung cancer (NSCLC) cell lines to investigate predictive biomarkers of response to R1507, a fully-humanized anti-IGF-1R monoclonal antibody (Ab; Roche)." (PMID 19806209, 2009). "Kaempferol may regulate EGFR/PI3K/AKT and IGF1R/PI3K/AKT signaling pathways by targeting EGFR, IGF1R, PIK3R1 and Akt, and then play a role in the treatment of non-small cell lung cancer." (PMID 37533633, 2023). "Ceritinib is approved for the treatment of patients with Anaplastic lymphoma kinase (ALK)-positive metastatic non-small cell lung cancer (NSCLC) but can also inhibit the insulin receptor (INSR), the insulin-like growth factor 1 receptor (IGF1R) and ROS proto-oncogene 1 (ROS1)." (PMID 32224911, 2020). "Furthermore, the addition of h7C10, anti-IGF-1R monoclonal antibody (mAB), to cetuximab, EGFR mAB, in A549 non-small cell lung cancer (NSCLC) xenograft models of wild-type EGFR and activated RAS mutation led to growth inhibition, unlike cetuximab alone." (PMID 29843755, 2018). "LoVo cells expressed high levels of uncleaved pro-IGF-1R protein, represented by the band seen at ∼200 kDa and no mature receptor at 130 kDa, in contrast to A549 (non-small-cell lung carcinoma), DU145 (prostate) and MCF-7 (breast) cancer cell lines." (PMID 16819546, 2006).
non-small cell lung carcinoma (continued). "miR-7-5p is more of a tumor suppressor that represses oncogenic proteins such as EGFR, IGF1R, IRS-1, IRS-2, RAF1, PIK3CD, mTOR, and PI3K, in various cancers including PDAC, liver, breast, non-small cell lung carcinoma (NSCLC), colorectal (CRC) and ovarian." (PMID 31510100, 2019). "A fully humanized anti-IGF1R monoclonal antibody (figitumumab) has been tested in phase III clinical trials; however, no statistically significant improvement was demonstrated by administering figitumumab along with standard chemotherapy to patients with advanced non-small cell lung cancer (NSCLC)." (PMID 22438913, 2012). "However, a phase-III study with an anti-IGF1R antibody combined with erlotinib in advanced non-small-cell lung cancer was terminated recently for safety reasons and lack of efficiency (ClinicalTrials.gov Identifier: NCT00673049)." (PMID 20924377, 2010).